OR4N4 (olfactory receptor family 4 subfamily N member 4)
Description:
Odorant receptor.
Synonyms: OR15-1; OR15-5
Tractability: Antibody: UniProt places it where antibodies can reach, with medium confidence; UniProt predicts a signal peptide or a membrane-spanning region; its Gene Ontology location is reachable by antibodies, with medium confidence.
Gene: Protein-coding gene on chromosome 15 (22,094,522 to 22,095,862, forward strand). Ensembl gene ENSG00000183706.
Subcellular location: Cell membrane
Subcellular location (Human Protein Atlas): Centrosome
Pathways (Reactome):
Sensory Perception: Expression and translocation of olfactory receptors
Gene Ontology:
Molecular function: olfactory receptor activity; G protein-coupled receptor activity
Biological process: detection of chemical stimulus involved in sensory perception of smell; G protein-coupled receptor signaling pathway
Cellular component: plasma membrane; membrane
Homologues: Orthologues: macaque OR4N4 (94% identical), dog OR4N2B (85% identical), mouse Or4n4 (83% identical), rat Or4n4 (82% identical), mouse Or4n4b (80% identical), rat Or4n4 (80% identical). Paralogues in human: OR4N4C (99% identical), OR4N2 (83% identical), OR4N5 (82% identical), OR4M1 (52% identical), OR4M2 (51% identical), OR4M2B (51% identical), OR4D5 (49% identical), OR4E2 (47% identical), OR4Q3 (47% identical), OR4D1 (47% identical), OR4D11 (47% identical), OR4D2 (47% identical), and 116 more.
Diseases named in the same sentence as OR4N4 in open-access papers:
OR4N4 is named in the same sentence as 1 disease in open-access papers, as found by Europe PMC text mining. Sharing a sentence is not in itself a finding about the gene and the disease.
OR4N4 shares sentences with these, for which no sentence is quoted: breast carcinoma (1 paper).